LUM (lumican)
Diseases named in the same sentence as LUM in open-access papers (continued):
Sharing a sentence is not in itself a finding about the gene and the disease.
actinic keratosis (1 paper, 2022). A precancerous lesion of the skin composed of atypical keratinocytes. "Although, no study has linked lumican specifically with the types of skin changes in kwashiorkor, i.e. “flaky paint” or “peeling paint” dermatosis, reduction of lumican levels have been reported in skin diseases such as actinic keratosis and Bowen's disease." (PMID 35398787, 2022).
acute lung injury (1 paper, 2022). A condition of lung damage that is characterized by bilateral pulmonary infiltrates (pulmonary edema) rich in neutrophils, and in the absence of clinical heart failure. "Lipopolysaccharide (LPS)-induced acute lung injury (ALI) mouse models were intratracheally administered an adeno-associated virus (AAV) vector expressing lumican shRNA." (PMID 36059026, 2022).
adenoma (1 paper, 2017). A neoplasm arising from the epithelium. "In the present study we investigated lumican and versican protein expression in adenoma-to-carcinoma progression and their potential association with commonly occurring genomic alterations involved in that process." (PMID 28481899, 2017). "The aim of this study was to characterize versican and lumican protein expression in tumor progression and investigate their association with CNAs commonly associated with adenoma-to-carcinoma progression." (PMID 28481899, 2017). "In conclusion, in the present study protein expression of both lumican and versican was upregulated in high-risk adenomas and carcinomas compared to low-risk adenomas, indicating that they may play a role in adenoma-to-carcinoma progression." (PMID 28481899, 2017). "Lumican was upregulated in high-risk adenomas and CRCs, but its expression did not correlate to gain of any of the three chromosomal regions (8q, 13q, 20q) investigated in the present study." (PMID 28481899, 2017). "This may indicate that the potential tumor suppressor role of lumican (in the tumor stroma) is less relevant in colon adenomas, and that expression of lumican is increased in adenoma-to-carcinoma progression in response to the development of tumor stroma." (PMID 28481899, 2017). "The expression of lumican was more prevalent in epithelial cells of CRCs than of adenomas." (PMID 28481899, 2017). "Although previous work revealed higher mRNA expression levels of the LUM and VCAN genes in carcinomas compared to adenomas, we did not observe significant correlations between mRNA and protein levels." (PMID 28481899, 2017). "The chromosomal regions of the LUM and VCAN genes (12q21.3-q22 and 5q14.3, respectively) are not among the most commonly gained regions in adenoma-to-carcinoma progression." (PMID 28481899, 2017).
Autoimmunity (1 paper, 2023). The occurrence of an immune reaction against the organism's own cells or tissues. "Additional studies are required to expand our knowledge of the full extent of natural TLR9 ligands that lumican and other SLRPs interact with to regulate inflammation and autoimmunity." (PMID 37834438, 2023). "Our study provides molecular insights into lumican and CpG-DNA interactions that may lead to molecular targets for modulating TLR9-mediated inflammation and autoimmunity." (PMID 37834438, 2023).
B-cell lymphomas (1 paper, 2022). "Interestingly, a subset of the members in the SLRP protein family have been previously identified in B-cell Non-Hodgkin’s lymphomas including DCN, BGN, ASPN, FMOD, LUM, PRELP, and TSKU." (PMID 36873459, 2022).
Barrett esophagus (1 paper, 2010). Esophageal lesion lined with columnar metaplastic epithelium which is flat or villiform. "Gene expression profiling studies of Barrett’s esophagus and esophageal adenocarcinoma have reported a transcriptional upregulation (~5-fold) of LUM in tumors as compared to adjacent normal esophageal epithelium." (PMID 24281036, 2010).
basal cell carcinoma (1 paper, 2023). A carcinoma involving the basal cells. "Regarding the KEGG signaling pathways, the ecm receptor interaction, TGF-β signaling pathway, cell adhesion molecule cams, hedgehog signaling pathway, basal cell carcinoma, adipocytokine signaling pathway, etc. were differentially enriched in phenotypes with high LUM expression." (PMID 38129820, 2023).
Bicuspid aortic valve (1 paper, 2021). The presence of an aortic valve with two instead of the normal three cusps (flaps). "Furthermore, the pathophysiological mechanism of lumican in bicuspid aortic valve and aneurysm formation is still unknown, and additional studies are warranted." (PMID 33661915, 2021).
brain tumours (1 paper, 2022). "we have reported five co-regulated clusters via seven important co-expression genes (COL1A2, LUM, SPARC, THBS2, IL1B, CXCL8, THY1) interacting between five clusters of the brain tumours." (PMID 35045088, 2022).
colon adenoma (1 paper, 2017). An adenoma that arises from the colon. "Lumican and versican expression were both observed in neoplastic cells and in the tumor stroma of colon adenomas and carcinomas." (PMID 28481899, 2017).
experimental autoimmune encephalomyelitis (1 paper, 2022). An autoimmune demyelinating disease of the central nervous system that is produced experimentally in animals by the injection of homogenized brain or spinal cord in Freund's adjuvant. "Nonetheless, a study found that mice with lumican deficiency exhibited both earlier onset and increased severity of experimental autoimmune encephalomyelitis, a disorder characterized by neuroinflammation." (PMID 36434717, 2022).
fatty liver (1 paper, 2018). "To further determine which genes might play a significant role in the progression of fatty liver, we used real-time qPCR to detect the expression of 8 DEGs using clinical samples, including CD24, PZP, COL1A1, COL1A2, LUM, VCAN, THBS2 and EPHA3." (PMID 29769552, 2018).
fibrosarcoma (1 paper, 2020). A malignant mesenchymal fibroblastic neoplasm affecting the soft tissue and bone. "The cleavage cancelled out the antitumour effect of lumican on a fibrosarcoma cell line." (PMID 32576155, 2020).
glomerulopathies (1 paper, 2023). "Moreover, it should be noted that a number of new potential markers that could be used to distinguish between severe glomerulopathies—such as APOM, ITOH2, and LUM—were identified." (PMID 37110557, 2023).
hepatocellular carcinoma (1 paper, 2023). A malignant tumor that arises from hepatocytes. "Notably, it was evident from the immunohistochemical images that LUM expression in hepatocellular carcinoma was lower than that in normal liver tissue, and LUM protein expression in liver tissue was mainly concentrated in hepatocytes rather than cholangiocytes." (PMID 37692065, 2023).
histiocytic sarcoma (1 paper, 2016). An aggressive malignant neoplasm with a poor response to therapy, usually presenting as stage III/IV disease. "Finally, upregulation of GTSF1, LUM, and PYPH and downregulation of CLEC12A and CD9 in primary canine histiocytic sarcomas were found to be dysregulated similarly in 3132 cells." (PMID 27639374, 2016).
hyperplastic (1 paper, 2024). "Recent studies confirmed that LUM was abundantly expressed in stroma of hyperplastic prostate, however, the role of LUM in BPH are remain undefined." (PMID 38459501, 2024).
hypertrophic obstructive cardiomyopathy (1 paper, 2024). "Proteomics studies demonstrate LUM as a highly expressed protein in hypertrophic obstructive cardiomyopathy and in oral submucous fibrosis." (PMID 38474072, 2024).
hyperuricemia (1 paper, 2024). An abnormally high level of uric acid. "Administration of either recombinant lumican or urate-lowering therapy effectively mitigated this TGFβ-driven anomalous myofibroblast activation, decelerating hyperuricemia-associated MI progression." (PMID 39482719, 2024). "Furthermore, we found that hyperuricemia decreases lumican levels secreted by cardiac fibroblasts, which underlies its negative impact on MI." (PMID 39482719, 2024). "We found that in hyperuricemia-related MI, lumican was derived mainly from fibroblasts in the infarct area rather than from macrophages, neutrophils, endothelial cells, or cardiomyocytes." (PMID 39482719, 2024). "We further employed western blotting and qPCR to evaluate lumican expression levels in hyperuricemia-related MI mice." (PMID 39482719, 2024). "In particular, hyperuricemia contributes to MI progression by decreasing fibroblast-derived lumican levels to activate the TGFβ/Smad2/3 signaling pathway, subsequently promoting fibroblast transition to myofibroblasts and enhancing adverse cardiac remodeling." (PMID 39482719, 2024). "In MI mice, lumican mRNA and protein expression significantly increased; however, hyperuricemia suppressed this increase." (PMID 39482719, 2024). "Hyperuricemia aggravates postinfarction cardiac remodeling by reducing lumican expression and promoting fibroblast phenotype transition." (PMID 39482719, 2024). "Collectively, these results show that lumican is derived mainly from cardiac myofibroblasts in hyperuricemia-related MI." (PMID 39482719, 2024). "Compared with the control conditions, hyperuricemia also decreased the plasma levels of lumican." (PMID 39482719, 2024). "However, hyperuricemia lowered lumican expression in MI mice and activated the TGFβ/Smad2/3 signaling pathway in cardiac fibroblasts to trigger adverse cardiac remodeling." (PMID 39482719, 2024). "The decreased lumican levels prompted us to determine whether the TGF-β signaling pathway was activated in hyperuricemia-related MI." (PMID 39482719, 2024). "This study suggests that lumican is a novel therapeutic target for hyperuricemia-related MI." (PMID 39482719, 2024). "Furthermore, the data confirmed that the effect of hyperuricemia is due to a shortage of fibroblast-derived lumican, which in turn promotes fibroblast activation and fibrotic function via the TGFβ/SMAD signaling pathway." (PMID 39482719, 2024). "Moreover, immunofluorescence staining revealed that the expression of lumican in the infarcted cardiac tissue decreased in response to hyperuricemia after MI compared with that in controls." (PMID 39482719, 2024). "Hence, we hypothesized that lumican might play a role in hyperuricemia-induced cardiac injury and that its increased expression following cardiac damage could serve as a compensatory mechanism." (PMID 39482719, 2024). "Our study focused on evaluating the effects of hyperuricemia on cardiac fibroblasts and the TGF-β/SMAD signaling pathway and explored the potential role of lumican as a biomarker." (PMID 39482719, 2024).
intervertebral disc degeneration (1 paper, 2021). "This study was designed to investigate the function and mechanism of LUM in intervertebral disc degeneration (IDD)." (PMID 34516336, 2021).
invasive carcinoma (1 paper, 2025). A carcinoma that is not confined to the epithelium, and has spread to the surrounding stroma. "Lumican is also differentially expressed during tumor progression form normal tissue to invasive carcinoma." (PMID 40927672, 2025).
liver cirrhosis (1 paper, 2022). "The altered ECM landscape in liver cirrhosis include the upregulation of collagens (type I, III, IV, V, VI, VIII, X, XI, XII, XIV, XV, XVI, XVIII, XXI), proteoglycans such as versican, decorin, lumican, and glycoproteins including fibulins, fibronectin, and laminins (Dataset EV5)." (PMID 35579278, 2022).
liver disease (1 paper, 2021). "However, the exact roles of fibromodulin and lumican in (HCV-related) liver disease remain to be determined." (PMID 34065048, 2021). "Lumican expression correlated with the severity of the (HCV-related) fibrosis, and high levels of lumican were reported in the plasma of HCV-positive patients with liver disease." (PMID 34065048, 2021).
lumbar disc herniation (1 paper, 2023). "Lumican (LUM) is an important ECM glycoprotein in human cartilage tissue and is highly expressed in NP tissues extracted from patients with lumbar disc herniation." (PMID 37686041, 2023).
macular corneal dystrophy (1 paper, 2014). Macular corneal dystrophy (MCD) is a rare, severe form of stromal corneal dystrophy characterized by bilateral ill-defined cloudy regions within a hazy stroma, and eventually severe visual impairment. "Loss of keratan sulfate biosynthesis is responsible for macular corneal dystrophy in humans, and in animal models loss of the KSPG protein lumican leads to defective to collagen fibrillogenesis and corneal haze." (PMID 24465995, 2014).
metastatic tumor (1 paper, 2025). "Expression of COL2A1, COL11A1, COL6A1, COL6A2 and LUM tended to be higher in primary/metastatic tumor than in normal tissue." (PMID 40927672, 2025).
microphthalmia (1 paper, 2024). Congenital or developmental anomaly in which the eyeballs are abnormally small. "This study is the first to map the expression patterns of NID2, LUM, and COL4A1 in stem cell-derived OVs and show their association in microphthalmia." (PMID 38821055, 2024). "The upregulation of LUM and other ECM proteins such as NID2 and COL4A1 in microphthalmia patient OVs in contrast to the loss of Lumican in animal models of increased axial length may be indicative of an inversely proportional relationship between the ECM and axial length." (PMID 38821055, 2024). "The overproduction of ECM components, including LUM, NID2, and COL4A1 that encapsulate and infiltrate the OV, may potentially physically limit ocular growth and development, resulting in eye malformations such as microphthalmia." (PMID 38821055, 2024).
mucinous adenocarcinoma (1 paper, 2021). An invasive adenocarcinoma composed of malignant glandular cells which contain intracytoplasmic mucin. "We found that LUM expression was higher in mucinous adenocarcinoma than in adenocarcinoma (P value < 0.05)." (PMID 33493133, 2021).
mucinous tumors (1 paper, 2013). "Stromal lumican expression overall was less frequently observed in mucinous tumors (P = 0.005)." (PMID 22711178, 2013). "Stromal lumican expression overall in the tumor was also more present in MSS tumors and less frequently observed in mucinous tumors (both P = 0.005)." (PMID 22711178, 2013).
muscle atrophy (1 paper, 2022). The loss of muscle tissue due to inactivity or disease. "Interestingly, we noted that the muscle mass was significantly lower in muscles treated with AAV6-lumican shRNA than in those treated with AAV6-scrambled, although we did not note any other signs of muscle atrophy, such as internalized nuclei, loss of nuclei, and loss of morphology (data not shown)." (PMID 36077426, 2022).
myxofibrosarcoma (1 paper, 2021). A malignant fibroblastic neoplasm arising from the soft tissue. "Collagen chains α1, α2 and α3 of collagen VI and lumican were detected among top 30 proteins in both intramuscular myxoma and myxofibrosarcoma." (PMID 34957097, 2021). "In contrast to intramuscular myxoma, grade I myxofibrosarcoma uniquely expressed collagen XII chain α1 and collagen XIV chain α1, as well as five proteoglycans (lumican, proteoglycan 4, prolargin, decorin and biglycan)." (PMID 34957097, 2021).
neuronal tumor (1 paper, 2019). Neuronal brain tumors are an uncommon group of central nervous system tumors that arise from cells with neuronal differentiation. "Here, we report for the first time that LUM is a FOXO3-regulated gene involved in the cellular migration of neuronal tumor cells." (PMID 31861249, 2019). "In summary, these results indicate that FOXO3-mediated migration depends on LUM expression in neuronal tumor cells." (PMID 31861249, 2019). "Together, these findings demonstrate that FOXO3 induces the expression of LUM, and that RPG efficiently represses FOXO3-mediated LUM induction in neuronal tumor cells." (PMID 31861249, 2019).
osteoporosis (1 paper, 2021). A condition of reduced bone mass, with decreased cortical thickness and a decrease in the number and size of the trabeculae of cancellous bone (but normal chemical composition), resulting in increased fracture incidence. "Taken together, these results suggest that lumican plays an osteoprotective role by simultaneously increasing bone formation and reducing bone resorption, and thus represents a potential dual-action therapeutic target for osteoporosis." (PMID 33946862, 2021). "Thus, lumican plays an osteoprotective role by simultaneously increasing bone formation and decreasing bone resorption, suggesting that it represents a dual-action therapeutic target for osteoporosis." (PMID 33946862, 2021).
ovarian tumor (1 paper, 2021). "Analysis of tumor volumes demonstrated an inhibitory effect of endogenous lumican on ovarian tumor growth." (PMID 34885059, 2021).
pathological myopia (1 paper, 2009). Excessive axial myopia associated with complications (especially posterior staphyloma and CHOROIDAL NEOVASCULARIZATION) that can lead to BLINDNESS. "The purpose of the study is to analyze sequences of lumican and decorin genes with pathological myopia(PM) and control subjects to verify the relationship between lumican, decorin genes and PM in Northern Han Chinese." (PMID 20339468, 2009).
preeclampsia (1 paper, 2021). Preeclampsia is a hypertensive disorder of pregnancy that is characterized by new-onset hypertension with proteinuria presenting after 20 weeks of gestation, and depending on mild or severe forms may initially present with severe headache, visual disturbances, and hyperreflexia. "Nonetheless, it remains unclear how lumican, or the composition of the ECM generally, changes in the placenta; further, it is unclear how these changes influence trophoblast cells during preeclampsia." (PMID 34231169, 2021). "However, the change and influence of lumican, a vital member of extracellular matrix (ECM) molecules, on trophoblast cells during preeclampsia remain unclear." (PMID 34231169, 2021).
pregnancy disorder (1 paper, 2017). A disorder that is related to pregnancy. "Finally, we also identified five genes (PLCB1, LUM, ADCY7, IRF7, and EHHADH) that we predict to be important for pregnancy disorders and placenta development, although such links remains to be established." (PMID 29222466, 2017).
pulmonary arterial hypertension (1 paper, 2024). Pulmonary arterial hypertension (PAH) is a group of diseases characterized by mean pulmonary artery pressure >20 mmHg and elevated pulmonary arterial resistance leading to right heart failure. "LUM deficiency in pulmonary arterial smooth muscle cells promotes arterial remodelling and matrix stiffening in pulmonary arterial hypertension." (PMID 38474072, 2024). "LUM has a pivotal role in the modulation of pathological vascular remodelling in the lung, which can lead to pulmonary arterial hypertension and stiffening of lung tissue." (PMID 38474072, 2024).
Rectal Adenocarcinoma (1 paper, 2023). "Next, we identified that the missense mutation of LUM was the primary type of genetic alteration, and the E240K/* alteration was detected in three cases of SKCM, two cases of COAD, and one case of BRCA, LUAD, STAD, UCEC and Rectal Adenocarcinoma." (PMID 37692065, 2023).
renal fibrosis (1 paper, 2022). A final common manifestation of a wide variety of chronic kidney diseases characterized by glomerulosclerosis and tubulointerstitial fibrosis. "Elevated lumican levels may be related to the progression of renal fibrosis, which is in correlation with previous research." (PMID 35884827, 2022).
sarcopenia (1 paper, 2022). Progressive decline in muscle mass due to aging which results in decreased functional capacity of muscles. "Interestingly, intramuscular and systemic administration of lumican significantly protected against muscle loss in vivo, suggesting that lumican can be developed as a bio-drug against diseases associated with muscle loss, including sarcopenia." (PMID 36077426, 2022). "In the present study, we performed in vitro and in vivo experimental experiments to generate evidence demonstrating that lumican could promote myoblast differentiation as an exerkine, thus affording a novel therapeutic target against sarcopenia." (PMID 36077426, 2022).